CALD1 (caldesmon 1)
Diseases named in the same sentence as CALD1 in open-access papers (continued):
Sharing a sentence is not in itself a finding about the gene and the disease.
ovarian serous adenocarcinoma (1 paper, 2024). An adenocarcinoma that arises from the ovary and is characterized by the presence of malignant epithelial cells that, in well differentiated tumors, resemble the epithelium of the fallopian tube or, in poorly differentiated tumors, show anaplastic features and marked nuclear atypia. "Analysis of patient data with ovarian serous adenocarcinoma from the TCGA database using GEPIA 2 confirmed a positive correlation between CYR61 and CALD1, supporting the potential association between CALD1 and CYR61 in platinum resistance of OC." (PMID 38365611, 2024).
ovarian serous cystadenocarcinoma (1 paper, 2024). A malignant serous cystic epithelial neoplasm arising from the ovary. "Subsequently, to further investigate the potential molecular mechanism and biological function of CALD1 in ovarian serous cystadenocarcinoma, the LinkInterpreter module of LinkedOmics were utilized to analyse function enrichment." (PMID 38365611, 2024). "A total of 9065 genes represented by red dots were positively correlated with CALD1, while 10,966 genes represented by green dots were negatively correlated with CALD1 in ovarian serous cystadenocarcinoma." (PMID 38365611, 2024).
periodontitis (1 paper, 2023). An acute or chronic inflammatory process that affects the tissues that surround and support the teeth. "Some research has suggested that CALD1 may be involved in the development of periodontitis, a type of gum disease characterised by inflammation and loss of the tissue and bone that support the teeth." (PMID 36982508, 2023). "It was found that CALD1 expression was significantly increased in the gingiva of people with periodontitis compared to those without the condition and that CALD1 may be involved in the immune response to periodontitis." (PMID 36982508, 2023).
psoriasis (1 paper, 2023). An autoimmune condition characterized by red, well-delineated plaques with silvery scales that are usually on the extensor surfaces and scalp. "Through TMT as one of isobaric labeling tags-based quantitative proteomic analysis and subsequent verification using ELISA, we especially identified three novel biomarkers associated with CVD risks in patients with psoriasis; CALD1, ZYX, and MNDA." (PMID 36804462, 2023). "Three novel candidates (MNDA, ZYX, and CALD1) could be potential biomarkers for predicting CVD risks in psoriasis patients." (PMID 36804462, 2023). "In this study, we found that differences in the expression of CALD1, ZYX, and MNDA between psoriasis with cardiovascular risk factors and those without cardiovascular risk factors were significant." (PMID 36804462, 2023).
pterygium (1 paper, 2021). A wedge-shaped fibrovascular lesion arising from the bulbar conjunctiva and extending to the cornea. "In addition, analyzing the expression of CALD1, DES, and SMTN, which are three known markers of smooth muscle cells being absent in myofibroblasts, revealed a significant downregulation or comparable expression in pterygium samples when compared to healthy conjunctiva." (PMID 35174178, 2021).
pulmonary fibrosis (1 paper, 2024). Chronic progressive interstitial lung disorder characterized by the replacement of the lung tissue by connective tissue, leading to progressive dyspnea, respiratory failure, or right heart failure. "Upon discovering the elevated expression of CALD1, CDH2, and POSTN in pulmonary fibrosis, we designed two pairs of siRNA for each gene to effectively knockdown their expression in HLFs." (PMID 38370408, 2024). "CALD1, CDH2, and POSTN, identified as potential contributors to pulmonary fibrosis, present promising therapeutic targets for IPF patients." (PMID 38370408, 2024). "Within this intersection, three hub genes, CALD1, CDH2, and POSTN, were found to be dysregulated and potentially significant in the context of pulmonary fibrosis." (PMID 38370408, 2024). "Furthermore, knockdown of CALD1, CDH2, and POSTN led to a reduction in TGF-β1-induced fibrotic markers, suggesting their potential roles in the development of pulmonary fibrosis." (PMID 38370408, 2024).
Thrombocytopenia (1 paper, 2020). A reduction in the number of circulating thrombocytes. "The dose‐limiting toxicity of Vorinostat was thrombocytopenia, which caused a transient reduction and pause (patient CALD1) or permanent withdrawal (patients CALD2 and CALD3) of Vorinostat." (PMID 32359032, 2020).
ulcerative colitis (1 paper, 2024). An inflammatory bowel disease involving the mucosal surface of the large intestine and rectum. "Interestingly, APOE, C1QB, and matrix metalloproteinase 12 (MMP12) are highly expressed in C1QB+ macrophages, IL-1B+ macrophages and CALD1+ macrophages from ulcerative colitis patients." (PMID 39095853, 2024). "Moreover, we also portrayed 5 subpopulations of monocytes, C1QB+ macrophages, CALD1+ macrophages, IL-1B+ macrophages, and SERPINA1+ macrophages in the intestinal mucosa from ulcerative colitis patients." (PMID 39095853, 2024).
tumor (43 papers, 2010 to 2025). "CALD1 encodes a calmodulin-binding protein, which is closely related to tumor-associated fibroblasts in BLAC and significantly affects the progression and prognosis of BLAC." (PMID 39590360, 2024). "CALD1 was associated with pro-tumorigenic M2 macrophage infiltration in the tumor microenvironment, which is known to exert anti-inflammatory, immunosuppressive, and proangiogenic characteristics." (PMID 36768598, 2023). "An important role of CaD in multiple types of cancer is highlighted by the finding of tumor-specific splicing variants of the CALD1 gene in cancer tissues including colon, urinary bladder, and prostate cancer." (PMID 36768598, 2023). "The Estimation of STromal and Immune cells in MAlignant Tumor tissues using Expression data (ESTIMATE) algorithm and correlation analysis revealed that CALD1 was significantly associated with multiple immune and stromal components in a tumor microenvironment." (PMID 33996905, 2021). "It was also approved for the first time that CALD1 regulated the tumor microenvironment associating with CAFs and macrophages." (PMID 34051818, 2021). "We hereby report that ANXA1 and CALD1 proteins are independent markers for tamoxifen therapy outcome and are associated to fast tumor progression." (PMID 26657294, 2016). "Moreover, CALD1 has been found to be associated with various immune cells and immune components in the tumor microenvironment." (PMID 38717641, 2024). "In particular, CALD1 was found to be strongly related to several immune as well as stromal components of the tumor microenvironment, and CALD1 levels in GC were closely associated with infiltration of immune cells, including dendritic cells, T cells, and tumor-associated macrophages." (PMID 38025524, 2023). "CALD1 isoforms have also been associated with tumour malignancy in several cancers." (PMID 37443771, 2023). "Previously, it has been shown that CALD1 may stimulate and polarize tumor-associated macrophages, and this is consistent with our findings but the specific mechanism remains poorly understood and further investigations are needed." (PMID 35692390, 2022). "The association between CALD1 and the tumor microenvironment was investigated." (PMID 34070840, 2021). "Using the reads mapping to the transcript encoding for the reporter (dsRED) we selectively identified the tumor cells, which we found to express a mesenchymal signature of transcripts encoding for extracellular matrix genes and collagens (Col1a1, Col1a2, Cald1, Calu)." (PMID 38509063, 2024). "Therefore, CALD1 might closely associate with the tumor microenvironment by affecting immunocyte infiltration and tumor angiogenesis." (PMID 34070840, 2021). "Therefore, CALD1 affected tumor microenvironment and was highly associated with tumor angiogenesis." (PMID 34070840, 2021). "This cohort showed a tendency for CALD1 gene expression to increase with tumor stage until stage III, and then started to decline." (PMID 36768598, 2023). "We also found that CALD1 levels increased in tumor tissues and GC cell lines compared to those in paraneoplastic tissues and the GES-1 cell line, respectively." (PMID 38025524, 2023). "Caldesmon (CALD1) is a cytoskeletal protein that regulates cell morphology and movement through interactions with actin filaments, and is closely related to tumor cell migration, invasion, metastasis and blood vessel formation." (PMID 35127818, 2021). "The CIBERSORT and ESTIMATE algorithms demonstrated significant correlations between CALD1 and the tumor microenvironment components, including CAFs, macrophages, T cells, and multiple immune checkpoint related genes." (PMID 34051818, 2021).
tumor (continued). "In multivariate Cox analysis, CALD1 (HR = 1.868, 95% CI: 1.165–2.995, P = 0.009), chemotherapy (HR = 1.869, 95% CI: 1.124–3.109, P = 0.016), and tumor stage (HR = 2.658, 95% CI: 1.414–4.996, P = 0.002) remained to be significantly correlated with OS." (PMID 33996905, 2021). "RBPMC2 and DSC3 were found as independent prognostic biomarkers of tumor progression and CALD1 and LCOR were identified as prognostic biomarkers of CSS between both groups." (PMID 33731721, 2021). "More stromal cells such as endothelial cells infiltrated in high l-CALD1 expression samples further supported the connection between l-CALD1 and tumor angiogenesis." (PMID 34070840, 2021). "More fibroblasts, endothelial cells, smooth muscle and microvascular endothelial cells were observed in the microenvironment of tumor with high CALD1 expression compared with the low CALD1 expression samples." (PMID 34070840, 2021). "Age, chemotherapy, tumor stage, COL1A2, and CALD1 were significantly associated with worse prognosis (P < 0.05)." (PMID 33996905, 2021). "Stromal cells proportion in the tumor microenvironment was analyzed, along with the CALD1 expression." (PMID 34070840, 2021). "The map of the tumor microenvironment also depicted that more stromal cells, such as endothelial cells and pericytes, infiltrated in high CALD1 expression samples." (PMID 34070840, 2021). "Consistent with above data for tumours generated from L1low cells, we found that tumours generated from shL1 cells showed increased extracellular matrix (eosin) content, expression of CALD1 and KERATIN 17 as evidenced by IHC." (PMID 32291413, 2020). "Intriguingly, L1low tumours showed an increased expression of the poor-prognosis stromal specific markers CALD1." (PMID 32291413, 2020). "Quantification of eight pairs (excluding two pairs with Ksucc expression levels in tumor tissues too low to be quantified) showed that the decreased level of Ksucc-K569 in CALD1 is statistically significant (p = 0.010)." (PMID 28165029, 2017). "In order to confirm our MS findings, we performed IHC stainings of both ANXA1 and CALD1 in an independent cohort of FFPE ER positive tumor tissues captured in a TMA to assess the clinical relevance of these markers." (PMID 26657294, 2016). "Overall, these data suggest a significant relationship between ANXA1 and CALD1 positivity and early tumor progression after tamoxifen treatment for recurrent ER positive breast cancer." (PMID 26657294, 2016). "ANXA1 and CALD1 staining only were observed in 17 and 16 tumor tissues, respectively, while only 4 tumors showed co-expression of the two markers." (PMID 26657294, 2016). "Using this replication population of samples, they were able to detect seven genes with tumour-specific splice variants (ACTN1, CALD1, COL6A3, LRRFIP2, PIK4CB, TPM1 and VCL)." (PMID 24179441, 2013). "Another feature of the diffuse subtype, active cell mobility, e.g., over-expression of Caldesmon 1 (CALD1), stimulates the invasion and metastasis of tumor cells." (PMID 21435268, 2011). "Furthermore, Pearson’s analysis revealed that miR-1278 and CALD1 levels were inversely correlated in the tumor tissues." (PMID 38025524, 2023). "Previous studies have demonstrated high CALD1 expression in GC accompanied by increased immune cell infiltration, suggesting that CALD1 may influence GC progression by regulating the immune microenvironment in tumor cells." (PMID 38025524, 2023). "We observed an increase in the expression of specific markers such as Caldesmon 1 (CALD1) (p = 0.0188), Tumour Endothelial Marker 8 (TEM8) (p = 0.0001) and C-X-C motif chemokine receptor 4 (CXCR4) (p = 0.0048) when CAM was treated with the pro-angiogenic VEGF at 200 ng/mL." (PMID 35644891, 2022). "At the same time, in tumor specimens with different stages and depth of tumor invasion, we found significantly differentially expressed CALD1 level, which further indicated that CALD1 has the potential to be used as a marker of BLCA progression." (PMID 34051818, 2021).
tumor (continued). "The HeLa-type CALD1 isoforms are localized in tumor vessels and could play a relevant role in promoting tumor angiogenesis, a phenomenon particularly pronounced in MBSHH." (PMID 30279357, 2018). "In this perspective, CALD1 may be another key effector in cytoskeletal rearrangements and the acquisition of a rapid spreading tumor phenotype in breast tissue, while countering those effects in other tissue types." (PMID 26657294, 2016). "Furthermore, similar analyses were performed in the GSE41258 validation dataset, and multivariate Cox analysis identified that both CALD1 (HR = 1.859, 95% CI: 1.095–3.158, P = 0.022) and tumor stage (HR = 4.951, 95% CI: 2.755–8.929, P < 0.001) were independent prognostic predictors." (PMID 33996905, 2021). "Therefore, CALD1 may be associated with the immunosuppression status of TME in BLCA, which further leads to tumor progression." (PMID 34051818, 2021). "Studies have identified CALD1 as an EMT transcription factor and a target of numerous genes regulating tumor EMT." (PMID 38717641, 2024). "Analysis of paired samples with both FFPE tissues and fresh frozen tumors showed that transcript levels of ACTA2, TPM2, CALD1, and TAGLN were significantly and positively correlated with the stromal percentage of the tumor." (PMID 37296997, 2023). "We further validated CALD1 for its roles in TME components and tumor progression at both the gene expression and cellular level." (PMID 33996905, 2021). "Unfortunately, the insufficiently acknowledged benefits of the l-CALD1 expression and distribution exist for GBM and tumor microenvironment." (PMID 34070840, 2021). "Progressive and de novo MIBC groups present different prognostic biomarkers for tumor progression (RBPMS2 in progressive MIBC and DSC3 in de novo MIBC) and for CSS (CALD1 in progressive MIBC and LCOR in de novo MIBC)." (PMID 33731721, 2021). "SULT1A2 (RI, 1.2:1.3) and CALD1 (ES, 8.3:9) exhibit the highest Δmedian PSI values between healthy and tumor tissues, in both left and right." (PMID 32293332, 2020). "In addition to this, we analyzed whether the associations of ANXA1 and CALD1 with TTP were independent of each other in the subset of 235 tumor tissues for which both measurements were available." (PMID 26657294, 2016). "At 12 h treatment, gefitinib induced the expression of HDAC5, a growth inhibitory tumor suppressor and pro-apoptotic factor, in Hec50co cells, while regulators of cell migration and morphogenesis such as GIT1 and CALD1 were down-regulated by gefitinib." (PMID 20579378, 2010). "Meanwhile, various functions regulated by CALD1, such as cell adhesion and leukocyte transendothelial migration, are closely related to the MAPK and TGF-β signaling pathways, which play a crucial role in both the proliferation and migration of tumor cells." (PMID 38025524, 2023). "Concomitant with the overexpression of AQP4, genes related to the immune system were also over-expressed, such as CD74, HES1, CALD1, and HEBP2, indicating AQP4 may relate to immune factors of tumor progression." (PMID 36599974, 2023). "Moreover, co-expression was found between CALD1, ACTA2 and CD206 in the tumor stroma, especially in patients with advanced BLCA." (PMID 34051818, 2021). "Due to the fact that only CALD1 showed significant association with the type of response, while ANXA1 displayed only borderline significance, combination of ANXA1 and CALD1 stainings was not performed using tumor response as the endpoint of tamoxifen therapy." (PMID 26657294, 2016). "A subgroup of the tumour-specific splicing variations (ACTN1, CALD1, and VCL) was observed in all three organs and may indicate general cancer-related splicing events." (PMID 24179441, 2013). "In the future, more investigations should be performed to confirm if CALD1 affects the survival of CSCs through the collation of PI3K signal or MAPK signal, and whether it interacts with the tumor-related molecule CYR61 to promote the progress of drug resistance." (PMID 38365611, 2024).
tumor (continued). "In addition, by siRNA-mediated CALD1 depletion in CRC cell lines, we found that the proliferation and metastasis ability of tumor cells were repressed, which indicated that CALD1 played a dual role in immunosuppression and tumor metastasis." (PMID 33996905, 2021).